SIRT3 (sirtuin 3)
Diseases named in the same sentence as SIRT3 in open-access papers (continued):
Sharing a sentence is not in itself a finding about the gene and the disease.
tumor (continued). "Therefore, although SIRT3 is negatively correlated with tumor immune infiltration, the effect of immune infiltration on NSCLC cells in this research still needs to be explored in subsequent experiments." (PMID 39501597, 2024). "SIRT3 regulates tumor progression by adjusting the acetylated modifications to a normal state." (PMID 38773972, 2024). "Additionally, SIRT3 also reprograms cellular lipid metabolism in tumor cells by regulating lipid metabolism enzymes." (PMID 38773972, 2024). "Interestingly, acetylation at lysine 258 on ACO2 modulates its function, and SIRT3 reverses this acetylation to suppress tumor progression." (PMID 39796040, 2024). "In cancer, SIRT3 targets different enzymes regulating oxidative stress and cell metabolism thus acting as a tumoral promoter, by maintaining ROS content under specific thresholds, or tumor suppressor by triggering cell death under stress conditions." (PMID 38811901, 2024). "Furthermore, the modulation of SIRT3 function can also be achieved by targeting its interacting protein network, which has emerged as a potential tumor intervention option by promoting or inhibiting protein-protein interactions." (PMID 38773972, 2024). "Moreover, SIRT3 activity is exploited by tumor cells to survive in an acidic microenvironment through the modulation of the autophagic process." (PMID 38931477, 2024). "Moreover, understanding the regulatory mechanisms of SIRT3 in different cancers can aid in designing drugs that either enhance its tumor-suppressive functions or inhibit its oncogenic activities." (PMID 38773972, 2024). "Targeting SIRT3 may provide promising therapeutic strategies by restoring its tumor-suppressive functions and improving treatment responses." (PMID 39796040, 2024). "The role of SIRT3 in various tumor types remains controversial." (PMID 38395990, 2024). "For instance, strategies aimed at restoring the tumor-suppressive functions of SIRT3 or enhancing SIRT4 activity could reverse metabolic reprogramming and tumor survival mechanisms." (PMID 39682281, 2024). "Thus, SIRT3's influence on cancer appears to be context-dependent, acting as either an oncogene or a tumor suppressor based on the specific metabolic demands of the cancer type." (PMID 38773972, 2024). "In addition, ADTL-SA1215 exerted anti-tumor effects by targeting SIRT3-regulated autophagy in a TNBC mouse xenograft model." (PMID 39479446, 2024). "Tumor volume was significantly lower in the SIRT3 mimics group than in the Vector group." (PMID 37747648, 2023). "We therefore inferred that Sirt3 might safeguard tumorigenesis before tumor occurrence but may accelerate tumor development after tumor established." (PMID 36739437, 2023). "Recently, SIRT3’s role as a mitochondrial localized tumor suppressor was identified." (PMID 37646973, 2023). "In addition, our findings reveal a novel mechanism in the holistic picture of 5-Fu-induced tumor cell death, partially by inhibiting SIRT3-regulated one-carbon metabolism." (PMID 37507016, 2023). "Recent studies have shown that by targeting a range of crucial regulators and their relevant pathways, SIRT-3 may perform the role of either a tumor suppressor or oncogene by affecting cell growth, leading to a decrease in cell proliferation." (PMID 36906524, 2023). "We observed a loss of Sirt3 and a concomitant elevation of LONP1 in tumor samples." (PMID 36739437, 2023). "In addition, SIRT3 can maintain tumour cell survival via interaction with permeability transition pore (cyclophilin D)." (PMID 37996927, 2023). "From these results, these authors showed that chrysin and CCNPs were potent inhibitors not only of SDH but also the regulator SIRT-3 and could prevent tumor progress in A549 and PANC-1 cells." (PMID 36906524, 2023).
tumor (continued). "Besides its role as an antiapoptotic, SIRT3 overexpression enhances the balance of ROS production in tumour cells which renders them resistant to chemotherapeutic drugs." (PMID 37996927, 2023). "In addition, SIRT3 promotes tumour cell autophagy and drug resistance through theregulation of PI3K/mTOR pathway and downregulation of P26." (PMID 37996927, 2023). "SIRT3 in hypoxic environments may affect tumor cell proliferation, invasion, migration, and inflammation levels via the ROS-FPR1/HIF-1α axis, thereby inhibiting tumor cell development." (PMID 37747648, 2023). "Furthermore, our results suggested that treatment with matrine and berberine upregulated the expression of Sirt3 in tumorous tissue." (PMID 37404762, 2023). "Previous studies have reported that upregulation of SIRT3 gene may results in reduction in apoptotic power and increased survival capacity of tumor cells, which ultimately leads to increased aggressiveness of tumor." (PMID 36809279, 2023). "The function of this gene may vary depending on the cell and tumor type; as a result, SIRT3 may operate as an oncogene or a tumor suppressor." (PMID 36624687, 2023). "On the other hand, the regulation of autophagy by SIRT3 could have a suppressive effect on tumor growth and elimination." (PMID 37765074, 2023). "Furthermore, resveratrol can induce autophagy by upregulating SIRT3 and phosphorylated AMPK, suggesting that the resveratrol-mediated inhibition of tumor progression is attributed to the participation of the SIRT3/AMPK/autophagy signaling axis." (PMID 37895359, 2023). "Thus, our finding that the deacetylation of LONP1 by Sirt3 constrains carcinogenesis need to be confirmed in other tumor cell lines." (PMID 36739437, 2023). "Hence, the anti-ferroptosis effect of SIRT3 in tumor cells potentially functions in the mitochondria." (PMID 37153222, 2023). "Its related study mechanism confirms that SIRT3 may inhibit tumor cell progression via the ROS-FPR1/HIF-1α axis." (PMID 37747648, 2023). "In addition, the mRNA and protein expression levels of SIRT3 were significantly down-regulated in tumor tissues in the Hypoxia group compared with the Control group." (PMID 37747648, 2023). "Besides, SIRT3 protects tumor cells against apoptosis in unfavorable environments, such as hypoxia and high glucose." (PMID 34747319, 2022). "Thus, increased Sirt3 expression attenuates glycolysis and cancer cell proliferation, both of which represent a metabolic mechanism for tumor suppression." (PMID 35938164, 2022). "A study by Zhang’s team demonstrated that SIRT3 is a tumor suppressor in HCC." (PMID 35571098, 2022). "Whereas, SIRT3 has been described as a tumor suppressor in BC12." (PMID 36167713, 2022). "Furthermore, UTMD delivery of Sirt3 in mice bearing SKOV3 xenograft tumor suppressed tumor volume and weight with an attendant decrease in Ki67 positive cells." (PMID 36132133, 2022). "The opposite effects of SIRT3 on apoptosis may due to the different characteristics of primary hepatocytes and tumor cells." (PMID 35923224, 2022). "The roles of SIRT3 vary in different cancers and have cell- and tumor-type specificity." (PMID 35571098, 2022). "Oppositely, SIRT3 also endows tumor cells with resistance to chemotherapy." (PMID 35832551, 2022). "Interestingly, SIRT3 can also function as a pro-apoptotic signal in some cancer cells, acting as a tumor-suppressing cell guard." (PMID 35671305, 2022). "SIRT3, a potential tumor suppressor in some solid cancers, was also down-regulated in PDAC." (PMID 35392973, 2022). "However, given the limited information in this research area, further investigations are required to fully establish the tumor-promoting effect of SIRT3 before a conclusion can be reached." (PMID 36291902, 2022). "The tumor-promoting effect of SIRT-3 is mainly related to the maintenance of cancer stem cells." (PMID 35906622, 2022).
tumor (continued). "Inhibition of FAO by overexpressing HES1 alleviated SIRT3-induced chemoresistance in AML, suggesting that HES1 may be one of the key tumor suppressors outside the mitochondria targeted by SIRT3." (PMID 35955415, 2022). "This dichotomous role of SIRT3 in cancer progression could depend on the type, stage and microenvironment of the tumor, but also on NAD+ availability." (PMID 35393510, 2022). "ROS promotes tumor cell damage and apoptosis, and the effectiveness of these processes may be influenced by SIRT3 expression." (PMID 35267521, 2022). "SIRT3 could function as a tumor suppressor to limit ROS levels via the activation of antioxidant enzymes, such as superoxide dismutase (SODs)." (PMID 35832551, 2022). "In summary, the function of SIRT3 varies in different cancers, with SIRT3 having cell-and tumor-type specificity, and its role may largely depend on the cellular conditions." (PMID 35571098, 2022). "This rationale leads some authors to suggest tumor suppressor functions of SIRT3." (PMID 35178152, 2022). "Chemotherapeutic agents, such as doxorubicin, cisplatin, oxaliplatin, and epirubicin, could inhibit the expression of SIRT3 in tumor cells." (PMID 35832551, 2022). "Consequently, it is difficult to reconcile an oncogenic function of TRAP1 with its activation by SIRT3, if the latter plays a tumor suppressor role." (PMID 35393510, 2022). "Similarly, the in vivo study showed that downregulation of SIRT3 in OSCC cells had a mitigating effect on tumor burden in mice." (PMID 36060706, 2022). "The authors speculated that it may be after a relapse of B-ALL, the up-regulation of three metabolic genes of NADSYN1, PARP6 and SIRT3, was promoted in response to certain tumor factors." (PMID 36439178, 2022). "Of course, as a tumor promoter, SIRT3 also shows a dark side." (PMID 35832551, 2022). "Up to date, tumor-suppressive and oncogenic roles of SIRT3 were both discussed in BC." (PMID 35927590, 2022). "SIRT3 can modulate intracellular ROS levels to regulate tumor metabolism reprogramming." (PMID 35832551, 2022). "Therefore, the contribution of SIRT3 to ccRCC is as a tumor suppressor in both its development and progression." (PMID 35671305, 2022). "Sirt3 also facilitates autophagy and mitophagy, processes that may both suppress tumor development and protect tumor cells from death, thus supporting tumor growth." (PMID 35938164, 2022). "One of the pathways by which Sirt3 controls tumor growth is destabilization of HIF1." (PMID 35938164, 2022). "Therefore, investigating possible mechanisms of the activation of the Sirt3 tumor suppressor function is an important task in medical oncology." (PMID 35938164, 2022). "In the beginning, many studies reported SIRT3 as a tumor suppressor." (PMID 34650436, 2021). "On the contrary, some studies have shown that SIRT3 has a tumour suppressor effect." (PMID 34841698, 2021). "Indeed, although SIRT3 was reported to shift cellular metabolism toward increased glycolysis in some types of cancer, it acts as tumor suppressor by modulating ROS and limiting the oxidative damage in cellular components in other types of cancer." (PMID 34680344, 2021). "Because aggressive cancers use both respiration and glycolysis, a baseline expression of PGC1A and SIRT3 could help maintain respiration to support tumor growth." (PMID 34831420, 2021). "However, in HCCs, SIRT3 acts as a tumor suppressor, as it mitigates ROS-induced hepatocellular injury and interacts with glycogen synthase kinase 3 beta (GSK-3β) to induce Bax translocation to the mitochondria, causing apoptosis." (PMID 33920670, 2021). "In contrast, many studies reported SIRT3 as a tumor activator." (PMID 34650436, 2021).
tumor (continued). "Functions annotation of these identified genes, using the ingenuity pathway analysis (IPA), predicted cumulative actions of decreased cell viability/proliferation, tumor growth and reactive oxygen species (ROS), and increased apoptosis in response to SIRT3 knockdown." (PMID 33937086, 2021). "Likewise, low SIRT3 expression was associated with serum AFP levels, which has both diagnostic and prognostic value in the context of HCC, tumor multiplicity and high relapse rate, thus representing a prognostic marker of overall survival in HCC patients." (PMID 33920670, 2021). "There is also support for SIRT3 to be pro-apoptotic as well as a tumor suppressor." (PMID 34769236, 2021). "Although SIRT3 was described as a tumor promoter in some types of cancers by shifting cellular metabolism toward increased glycolysis, in other types of cancers SIRT3 acts a tumor suppressor by modulating ROS and limiting the oxidative damage in cellular components." (PMID 34360883, 2021). "Sirt3 K223R OT1 T cells were more potent in inhibiting tumour growth than Sirt3 WT-OT1 T cells." (PMID 34272364, 2021). "Though the administration of 4HR would inhibit the growth of tumor, elevated SIRT3 and SIRT6 could play a protective role for cancer cells that survived after 4HR treatment, and these cancer cells might be more resistant to other cytotoxic cancer therapy." (PMID 34719767, 2021). "Furthermore, another member of the family, SIRT3, has a dual role in cancer, as it can act as a tumor suppressor and promotor." (PMID 33669567, 2021). "However, other studies have described SIRT3 as a tumor suppressor with the ability to trigger cell death under stress conditions." (PMID 33669567, 2021). "Therefore, knockdown of these proteins would reduce mitochondrial plasticity and tumor growth in vivo, and thus SIRT3 would appear to have oncogenic effects." (PMID 34831420, 2021). "Importantly, it has been reported that SIRT3 can link to four hallmarks of cancer, such as genomic instability, sustained proliferation, dysregulated energetic status, and tumor-promoting inflammation." (PMID 33920670, 2021). "Interestingly, regarding to its inherent complexity, SIRT3 has been demonstrated to play the Janus role in cancer, indicating that SIRT3 activators or inhibitors would be utilized as anti-tumor agents in specific types of cancers, respectively." (PMID 32724473, 2020). "Sirt3 was shown to act as a tumor suppressor by inhibiting glycolysis metabolism through the deacetylation and consequent activation of pyruvate dehydrogenase, but it is also possible that it can act as a tumor promoter in some situations." (PMID 33203121, 2020). "Additionally, programmed cell death induction is another strategy SIRT3 uses to inhibit tumor progression." (PMID 32724473, 2020). "The most important tumor suppression role of SIRT3 is that it hinders cancer metabolism changes." (PMID 32724473, 2020). "Thus, the ability of A671 to stabilize SAP18 and to block SIRT3 expression is a potential biomarker of tumor responsiveness to the drug." (PMID 33273692, 2020). "Studies demonstrated that SIRT3 could repress tumor growth by downregulating HIF-1α and decreasing ROS accumulation to regulate the Warburg effect in cancer cells and inhibit tumorigenesis." (PMID 33298860, 2020). "In addition, low SIRT3 expression was significantly associated with poor overall survival and disease-free survival of KIRC patients, which is consistent with the previous view that SIRT3 act as a tumor suppressor." (PMID 32158696, 2020). "However, only few studies have investigated the effects of SIRT3 on tumor prognosis and sorafenib sensitivity in patients with HCC." (PMID 32306906, 2020).
tumor (continued). "Indeed, our data from a preclinical tumor model demonstrated that inhibition of SIRT3 signaling lead to suppression of ATM−/− xenograft tumor growth." (PMID 33273545, 2020). "SIRT3, a member of the mammalian sirtuin family, is a tumor suppressor in certain tumor types." (PMID 32306906, 2020). "Considering the tumor suppressive role of Sirt3, we hypothesized that E2/ERα signaling can be negatively affected by Sirt3." (PMID 32244715, 2020). "Our observations indicate that these tumor-suppressive effects of Sirt3 could be reversed by E2 treatment only to a limited extent which is not sufficient to recover the tumorigenic properties of the MCF-7 cells." (PMID 32244715, 2020). "FOXO3, a potential SIRT3 target, belongs to the forkhead box class O transcription factor family which can regulate various cellular and physiological processes, such as metabolism, development, and tumor suppression." (PMID 33298860, 2020). "Depressed mitochondrial respiration and stimulation of SIRT3 pathway might help to alleviate cellular load from mitochondrial dysfunction and oxidative stress for sustained tumor growth in ATM−/− DLBCL." (PMID 33273545, 2020). "Mechanistically, several lines of evidence support the tumor-suppressor activity of SIRT3 in HCC." (PMID 31060333, 2019). "There is a controversy whether these proteins act as oncogenes or suppressor genes in tumors, although there are literature data about a tumor-suppressive function of SIRT-3 and an oncogenic role of HIF-1α and p-mTOR in HCC." (PMID 30917505, 2019). "Of the three mitochondrial sirtuins, SIRT3 is the most well studied to date and has been long considered as a tumor suppressor by activating manganese superoxide dismutase (MnSOD), a mitochondrial antioxidant enzyme, decreasing ROS levels and maintaining the stabilization of HIF-1α." (PMID 31093315, 2019). "SIRT3 also has been found to be a tumor suppressor in the context of B cell malignancies, as a number of malignant B cell lines display decreased SIRT3 protein expression and higher ROS levels, and overexpression of SIRT3 in these lines decreased proliferative activity." (PMID 31354630, 2019). "The role of SIRT3 in neoplasia is cell-type specific and potentially quite complex." (PMID 30538800, 2018). "Interestingly, most tumor samples with high SHMT2 expression exhibited increased SIRT3 protein expression compared with adjacent normal tissues (P < 0.01)." (PMID 30367038, 2018). "NRF2 and SIRT3 were only down-regulated in the GBM50 tumours." (PMID 30208958, 2018). "SIRT3 regulates the Warburg effect by decreasing the high glycolysis rate in tumor cells." (PMID 27686535, 2017). "SIRT3 acts as a tumor suppressor by inhibiting ROS production and activation of HIF1α." (PMID 28423723, 2017). "Therefore, SIRT3 shows a dual role in cancer, as it can act as a tumour suppressor or a tumour promoter, depending on the cellular context." (PMID 28704962, 2017). "SIRT3, a member of the silent information regulator (Sirtuins) family, participates in cell biological functions such as energy metabolism and cell aging by regulating mitochondrial function, and it is closely related to tumor development and progression." (PMID 28947845, 2017). "To examine whether SIRT3 has a role in inhibiting tumor growth in vivo, we injected SIRT3-overexpressing AGS cells into the flanks of nude mice." (PMID 29108235, 2017). "On the contrary, some studies suggest a tumour suppressor role for SIRT3." (PMID 28704962, 2017). "SIRT3 has been reported to drive oncogenic and tumor-suppressive effects." (PMID 28634345, 2017). "SIRT3 is generally identified as a tumor suppressor by regulating several metabolic pathways." (PMID 27659520, 2017).